IL27 (interleukin 27)
Diseases named in the same sentence as IL27 in open-access papers (continued):
Sharing a sentence is not in itself a finding about the gene and the disease.
peritonitis (5 papers, 2014 to 2024). Inflammation of the peritoneum (tissue that lines the abdominal wall and covers most of the organs in the abdomen). "Pre-treatment with IL-27 led to a significantly decreased loss of neutrophils from the bone marrow as early as 4 h after induction of peritonitis." (PMID 26360023, 2015). "To further elucidate the anti-inflammatory effects of IL-27 on the innate immune system in vivo, we chose the zymosan-induced peritonitis as a robust model of acute innate inflammation." (PMID 26360023, 2015). "Here, we demonstrate that IL-27 treatment inhibits neutrophil accumulation at the site of inflammation in the T cell independent model of zymosan-induced peritonitis." (PMID 26360023, 2015). "To determine the role of IL-27 in innate immune responses we analysed the effect of IL-27 in a T cell independent model of zymosan-induced peritonitis." (PMID 26360023, 2015). "We investigated the role of IL-27 in sterile peritonitis induced by injection of zymosan into the peritoneal cavity." (PMID 26360023, 2015). "Thus, IL-27 treatment is able to reduce neutrophil accumulation in the peritonitis model, but effects show a lag phase of several hours." (PMID 26360023, 2015). "In the peritonitis model studied here, values of IL-17 were near the detection limit and the small decline upon IL-27 treatment was not significant." (PMID 26360023, 2015). "To confirm the ability of IL-27 to suppress leukocyte recruitment in the absence of a significant contribution from T cells, we determined the impact of IL-27 treatment in the T cell-independent zymosan-induced peritonitis model." (PMID 24809349, 2014). "To test the hypothesis that IL-27 treatment is able to suppress the accumulation of neutrophils independent of T cells, we applied rIL-27 in an acute model of TLR-induced sterile inflammation, the zymosan-induced peritonitis model." (PMID 24809349, 2014).
pneumococcal infection (5 papers, 2014 to 2024). Infections with bacteria of the species streptococcus pneumoniae. "During pneumococcal infection in mice, IL-10 production is required to temper an excessive lung injury and to improve survival, while IL-27 in combination with IL-6 are involved in the ability of AMs to ty to promote Treg cell responses." (PMID 37958756, 2023). "The concentrations of IFN-γ and IL-17 as well as of the immunoregulatory cytokines IL-10 and IL-27 were determined in BAL samples after the pneumococcal infection." (PMID 34207076, 2021). "Our study defines what we believe to be a novel role of IL-27 in impairing host innate immunity against pneumococcal infection." (PMID 24408967, 2014). "Our data thus indicate that the improved production of IL-10, IL-27, and IL-6 by AMs of 040417-treated infant mice may play an important role in limiting inflammation during the pneumococcal infection by increasing the protective functions of Treg cells." (PMID 34207076, 2021). "Finally, neutralization of IL-27 or administration of IL-17A restored the role of γδ T cells in combating secondary pneumococcal infection." (PMID 24408967, 2014). "Although pneumococcal infection alone was associated with some increase in IL-27 production, yet this response did not seem to be sufficient to impact pneumococcal infection, since lung pneumococcal burdens were unaltered in IL-27R-deficient mice." (PMID 24408967, 2014). "Hence, the induction of IL-27 did not affect the viral or pneumococcal clearance in naive mice, but markedly increased susceptibility to secondary pneumococcal infection." (PMID 24408967, 2014). "We found that inoculation of exogenous IL-27 could significantly down-regulate IL-17A production and the percentage of IL-17A-producing γδ T cells in the lungs of IFNAR-deficient mice after secondary pneumococcal infection." (PMID 24408967, 2014). "Furthermore, treatment with anti-IL-27 blocking antibodies could protect against secondary pneumococcal infection, indicating that immunomodulatory therapy aimed at antagonizing IL-27 may provide a potential therapeutic intervention for humans susceptible to postinfluenza pneumococcal pneumonia." (PMID 24408967, 2014). "In addition, it was reported that IL-27 production in an IFNAR-signaling-dependent manner induced by IFV impairs IL-17A-producing γδ T cells, leading to a reduced neutrophil response and resistance to a secondary pneumococcal infection." (PMID 32660087, 2020). "Therefore, we reported what we believe to be a novel negative role of IL-27 in IL-17A production by γδ T cells upon secondary pneumococcal infection." (PMID 24408967, 2014).
preeclampsia (5 papers, 2014 to 2023). Preeclampsia is a hypertensive disorder of pregnancy that is characterized by new-onset hypertension with proteinuria presenting after 20 weeks of gestation, and depending on mild or severe forms may initially present with severe headache, visual disturbances, and hyperreflexia. "The elevated serum level of IL-27 in women with severe preeclampsia suggests IL-27 as a useful biomarker for disease severity in preeclampsia." (PMID 34906158, 2021). "The study of tentative therapeutic methods targeting IL-27/IL-27RA/Wnt or SFRP2 is of great research significance in investigating trophoblast-related diseases, such as FGR, preeclampsia, miscarriage and so on." (PMID 36860682, 2023). "In the immunostaining of formalin-fixed paraffin-embedded serial sections, IL-27 and WSX-1 were also upregulated in the trophoblastic cells from the placenta of preeclampsia compared with control specimens." (PMID 24659862, 2014).
respiratory infections (5 papers, 2017 to 2023). "In C. muridarum-induced respiratory infection, our previous study found that IL-27/IL-27R protects the host by promoting the Th1 response and suppressing excessive IL-17-induced neutrophilic inflammation." (PMID 36985179, 2023). "Fitting with this we found that alveolar macrophages, (gated as in S5A Fig), the first professional immune cell to encounter respiratory infections, rapidly upregulated IL-27 after infection of mice with RSV." (PMID 28953978, 2017). "Here, we used the mouse model of Chlamydia muridarum (C. muridarum) respiratory infections to further investigate the impact of IL-27 signaling in the DCs-regulated immune response, since an elevated IL-27/IL-27R expression in DCs was identified following chlamydial infection." (PMID 36985179, 2023). "Several insights into IL-27 function in the lung have come from studies of respiratory infection." (PMID 30874596, 2019). "Although the beneficial role of IL-27 in regulating inflammation in the lungs has been described for several respiratory pathogens, there is a lack of studies directly investigating the effect of this regulatory cytokine in the context of K. pneumoniae respiratory infection." (PMID 37317122, 2023).
Stroke (5 papers, 2017 to 2025). Sudden impairment of blood flow to a part of the brain due to occlusion or rupture of an artery to the brain. "In our results, we observed higher levels of IL-27 in ICU controls (consisting of patients with stroke)." (PMID 35327327, 2022). "In an experimental stroke model, mice were administered IL-27 injections post-intracranial hemorrhage (ICH) and demonstrated improved behavior tests, mobility, and reduced edema around the hemorrhage sites." (PMID 32010048, 2019). "The seven important predictor genes (CCR4, IFNA2, IL-9, IL-7, IL-5, CCR3, and IL-27) that overlapped both stroke outcomes had mean fold change ranging from 3.98 to 35.06." (PMID 32010048, 2019). "In addition, flow cytometry on blood taken from animals at day 3 after stroke demonstrated that anti-IL-27-Ab significantly decreased the intensity of LTF per blood neutrophil (p = 0.02; n = 3/group) after ICH." (PMID 28928459, 2017). "The intersection of the top 10 genes from the two stroke outcomes are seven genes with T2DM, these include CCR4, IFNA2, IL-9, IL-7, IL-5, CCR3, and IL-27." (PMID 32010048, 2019). "Cytokine expression in both stroke types follows a biphasic pattern: an early pro-inflammatory phase dominated by TNF-α, IL-6, IL-1β, interleukin-27A (IL-17A), and high-mobility group box 1 (HMGB1), followed by a later anti-inflammatory phase marked by IL-10, TGF-β1, and interleukin-27 (IL-27)." (PMID 40868089, 2025).
abortion (4 papers, 2015 to 2025). the ending of pregnancy by removing a fetus or embryo before it can survive outside the uterus. "Although It seems that IL-27 may reduce inflammatory responses through human pregnancy, IL-27 -964 A>G polymorphism is a genetic marker for identifying women at increased risk of recurrent spontaneous abortion." (PMID 26131009, 2015). "The study observed that IL-27 expression was 10.39 times higher in patients experiencing spontaneous abortion compared to healthy pregnant women (p < 0.000001)." (PMID 40141672, 2025). "In patients with spontaneous abortion, a 10.39-fold increase in IL-27 expression was observed compared to healthy pregnant women." (PMID 40141672, 2025). "It was observed that the 2−ΔΔCT in the expression level of IL-27 in spontaneous abortion patients increased compared to healthy pregnant women, but this decrease was not statistically significant (p = 0.855)." (PMID 40141672, 2025). "Conversely, while IL-27 2−ΔΔCT values were higher in spontaneous abortion patients compared to healthy pregnant women, this increase was not statistically significant (p = 0.855)." (PMID 40141672, 2025). "Week of pregnancy, GAPDH, and IL-27 were significantly lower in spontaneous abortion patients than healthy pregnant women (p < 0.05)." (PMID 40141672, 2025). "To determine the role of the IL-27/Blimp-1 axis in the materno-fetal immune tolerance via the regulation of Tregs, we established an abortion-prone mouse model by injecting LPS intraperitoneally (i.p.)." (PMID 39171524, 2024). "Using both gene editing via AVV transfection to modify Tregs and IL-27 pretreated Tregs, the rescue effects of the transferred Tregs were further verified in the LPS-induced abortion-prone mouse model." (PMID 39171524, 2024). "We found that the transferring Blimp-1+ Tregs and IL-27–treated Tregs had similar effects in reducing embryo absorption rates and improving the placental vascular development in the LPS-induced abortion-prone mouse model." (PMID 39171524, 2024). "This study found that adoptively transferred TregsBlimp-1 and IL-27–treated Tregs have a certain improvement in the pregnancy outcome of the LPS-induced abortion-prone mouse model." (PMID 39171524, 2024). "Additionally, the median IL-27 level in spontaneous abortion patients was found to be 18.46 (18.14–18.76), while in healthy pregnant women it was 21.65 (21.35–21.91), with this difference also being statistically significant (p < 0.001)." (PMID 40141672, 2025). "In conclusion, the fold changes in IL-2, IL-17, and IL-27 expression levels between spontaneous abortion patients and healthy pregnant women reveal possible alterations in immune regulation that might contribute to spontaneous abortion." (PMID 40141672, 2025). "The significant decrease in IL-27 levels in spontaneous abortion patients may reflect the effects of this cytokine on immune response." (PMID 40141672, 2025). "The AT of TregsBlimp-1+ and IL-27–pretreated Tregs could improve pregnancy outcomes in an LPS-induced abortion-prone mouse model." (PMID 39171524, 2024). "Furthermore, we showed that IL-27 regulated the expression of Tim-3 and Blimp-1 through the STAT1 signaling pathway and that transfer of TregsBlimp-1+ into an abortion-prone mouse model effectively reduced embryo absorption rate." (PMID 39171524, 2024). "While IL-27 may play a role in spontaneous abortion, the lack of statistical significance in its expression limits the strength of this association in the present study." (PMID 40141672, 2025).
acute coronary syndrome (4 papers, 2019 to 2025). Signs and symptoms related to acute ischemia of the myocardium secondary to coronary artery disease. "This study evaluated changes in interleukin (IL)-27 levels in patients with acute coronary syndrome (ACS) and their influence on Th1, Th2, and Th17 cells." (PMID 30631648, 2019).
acute respiratory distress syndrome (4 papers, 2022 to 2025). Progressive and life-threatening pulmonary distress in the absence of an underlying pulmonary condition, usually following major trauma or surgery. "Given that increases in IL‐27 have been correlated with inflammatory reactivity and disease severity in acute lung injury/acute respiratory distress syndrome, the feedback regulation provided by IL‐10 likely contributes to its therapeutic effects." (PMID 39980189, 2025).
allergic rhinitis (4 papers, 2018 to 2025). Inflammation of the nasal mucous membranes caused by an IgE-mediated response to external allergens. "Another polymorphism in our study, rs178855750 (2905 T > G) is located in exon 2 of the IL-27 gene and has also been implicated in allergic rhinitis and cervical cancer." (PMID 30268141, 2018). "Interleukin-27 (IL-27) has been reported to inhibit type 2 T helper cell (Th2) response in allergic rhinitis (AR)." (PMID 33381604, 2020). "In animal models, intranasal administration of IL-27 decreased nasal allergic responses and symptoms even after the establishment of allergic rhinitis." (PMID 33381604, 2020).
bladder cancer (4 papers, 2015 to 2022). "Accordingly, the present study analyzed the influence of IL-27 polymorphisms and plasma levels of IL-27 on the susceptibility to bladder cancer and prognosis of patients." (PMID 26014498, 2015). "Taken together, the present study suggests that IL-27 gene polymorphisms are associated with susceptibility to bladder cancer." (PMID 26014498, 2015). "This study has analyzed the associations of IL-27 gene polymorphisms, as well as plasma levels of IL-27, with susceptibility to bladder cancer and clinical outcome." (PMID 26014498, 2015). "In the present study, we have identified significant associations between IL-27 SNPs and susceptibility to bladder cancer, patients’ characteristics, and overall survival of patients with MIBC." (PMID 26014498, 2015). "The present study identified that IL-27 gene is associated with susceptibility to bladder cancer." (PMID 26014498, 2015). "We didn’t find any influence of plasma IL-27 levels on the survival of patients, the present data suggested that decreased plasma IL-27 levels may be associated with increased susceptibility to bladder cancer." (PMID 26014498, 2015). "For the first time, our data suggested that polymorphisms of IL-27 gene may play important roles in the initiation, promotion, and progression of bladder cancer, especially in MIBC." (PMID 26014498, 2015). "Our data suggest that polymorphisms and reduced plasma levels of IL-27 may predict the susceptibility to bladder cancer, and rs17855750 may be a useful marker to distinguish patients with high risk of death." (PMID 26014498, 2015). "To summarize, IL-27 or sorafenib alone inhibited proliferation, migration and invasion and promoted apoptosis of bladder cancer cells, and the effects were augmented by their synergistic action." (PMID 28746469, 2017). "The combination of IL-27 and sorafenib inhibited proliferation, migration and invasion and promoted apoptosis of bladder cancer cells compared with mono-drug treatment." (PMID 28746469, 2017). "Based on the inhibition of IL-27 on tumor angiogenesis, we wished to study the combined effect of IL-27 and sorafenib on bladder cancer." (PMID 28746469, 2017). "By analyzing the plasma IL-27 concentration of 124 bladder cancer patients and 151 controls, we found significant difference among NMIBC, MIBC and controls (P < 0.0001)." (PMID 26014498, 2015). "Further studies with a larger number of patients and IL-27 gene therapy in bladder cancer cells are warranted to confirm these results." (PMID 26014498, 2015). "The decreased plasma levels of IL-27 compared to controls observed in our present study reinforces this predictive role as a marker of bladder cancer." (PMID 26014498, 2015). "Combined inhibition of IL-27 and other immune-checkpoint molecules may be a potential choice for bladder cancer patients with high levels of expression of CLRs." (PMID 36131933, 2022). "IL-27 has been reported to augment the anti-tumor effects of sorafenib on bladder cancer cells; thus, there could be promise for utilizing 27-related therapies for this cancer type." (PMID 34209203, 2021). "Future preclinical studies might examine the potential for evolving IL-27-based therapies and combinations with other cytokines for the treatment of bladder cancer." (PMID 34209203, 2021). "Taking into account the same effect of sorafenib and IL-27 on anti-tumor and antiangiogenesis, we reasoned that the combination of IL-27 and sorafenib might cooperate synergistically to treat bladder cancer." (PMID 28746469, 2017). "In our study, we interestingly found that IL-27 or sorafenib could inhibit cell proliferation, migration and invasion while promoted cell apoptosis of bladder cancer cells, and the combination of these two drugs significantly augmented the influence in HTB-9 cells." (PMID 28746469, 2017).
dyslipidemia (4 papers, 2015 to 2024). "It was demonstrated in an experimental study that atherogenic dyslipidemia enhances autoimmune responses in a Toll-like receptor 4 and IL-27-dependent manner." (PMID 34439776, 2021). "IL-27 levels may be a potential therapeutic target for dyslipidemia and NAFLD." (PMID 37600722, 2023).
esophageal cancer (4 papers, 2013 to 2022). A primary or metastatic malignant neoplasm involving the esophagus. "Together with a recent report that reduced serum IL-27 level is a risk factor for esophageal cancer, our data support the concept that IL-27 signaling agonists could be beneficial in immunotherapy for the treatment of cancer." (PMID 23554861, 2013).
Granuloma (4 papers, 2014 to 2021). A compact, organized collection of mature mononuclear phagocytes, which may be but is not necessarily accompanied by accessory features such as necrosis. "IL-27 affects host immune response against M. tuberculosis infection with elevated IL-27 levels reported in granuloma, lung, pleural fluid, and sputum during M. tuberculosis infections." (PMID 34079555, 2021). "It has previously been shown that large granulomas with diffuse foci of inflammatory infiltrates form in the liver in the absence of IL-27 signalling during L. donovani infection." (PMID 33049000, 2020). "In this study, the absence of IL27 due to EBi3 knockout could also have triggered a decrease in IFNɣ and a decrease in granulomas volume, since this cytokine is important in the acute phase of schistosomiasis." (PMID 32078636, 2020). "EBi3-/-I mice show decreased hepatic damage considering volume and reduced number of granulomas compared to WTI mice; the absence of IL27 and IL35 pathways decreases the Th1 response resulting in minor liver damage." (PMID 32078636, 2020).
Hypertension (4 papers, 2020 to 2024). The presence of chronic increased pressure in the systemic arterial system. "Although the association between the IL-12 family members and hypertension remains unknown, this study is aimed at detecting the levels of circulating IL-12, IL-23, IL-27, and IL-35 in hypertensive patients." (PMID 32322161, 2020). "Little research has been conducted regarding IL-23, IL-27, and IL-35 in relation to hypertension." (PMID 32194399, 2020). "However, whether IL-27 plays an inhibitory or promotive role in hypertension requires further investigation." (PMID 39906735, 2024). "IL-12, IL-23, and IL-27 levels gradually increased in patients with grade I, II, and III hypertension, while IL-35 levels gradually reduced." (PMID 32322161, 2020). "However, IL-35 exhibited an opposite trend compared to that shown by the IL-12, IL-23, and IL-27 levels in patients with grade I, II, and III hypertension and those from the control group." (PMID 32322161, 2020).